MIR106B (microRNA 106b)
Synonyms: hsa-mir-106b; MIRN106B; mir-106b
Gene: MicroRNA gene on chromosome 7 (100,093,993 to 100,094,074, reverse strand). Ensembl gene ENSG00000208036.
Gene Ontology:
Biological process: miRNA-mediated post-transcriptional gene silencing
Cellular component: RISC complex
Homologues: Orthologues: chimpanzee ptr-mir-106b (100% identical), pig MIR106B (100% identical), guinea pig MIR106B (99% identical), macaque mml-mir-106b (99% identical), mouse Mir106b (96% identical), dog MIR106B (70% identical). Paralogues in human: MIR20A (55% identical), MIR17 (54% identical), MIR20B (51% identical), MIR18A (48% identical).
Diseases named in the same sentence as MIR106B in open-access papers:
MIR106B is named in the same sentence as 3 diseases in open-access papers, as found by Europe PMC text mining. Sharing a sentence is not in itself a finding about the gene and the disease. The quoted sentences say what the papers report.
breast cancer (2 papers, 2022 to 2025). A primary or metastatic malignant neoplasm involving the breast. "Similarly, several exosome-derived miRNA orthologs previously reported for increased expression in both canine and human mammary tumor cell lines, including MIR21, MIR106B, MIR181A1, MIR183, MIR200B, and MIRLET7G, were presented." (PMID 35765483, 2022). "A total of six miRNA orthologs – MIR21, MIR30E, MIR106B, MIR10B, MIR200A, and MIR200B were identified as differentially expressed orthologs among mammary tumor cell lines, lymphoid tumor cell lines, and normal epithelial cell cultures (importance ≥10 and p≤0.01) (Figure-2)." (PMID 35765483, 2022).
tumor (2 papers, 2018 to 2022). "CASKIN2, TLE2, USP20, SPRN, ARSG, MIR106B, and MIR98 were considered to be substantially expressed in the low-risk group, suggesting that these genes may be PAAD tumor suppressor genes." (PMID 35077391, 2022). "Oral gavage of leucoselect phytosome (LP), a standardized GSE to athymic nude mice down-regulated MIR106B mRNA and miR-106b expressions, and increased CDKN1A mRNA expression in tumor xenografts, correlating to significant reduction of tumor growth." (PMID 29643994, 2018).
MIR106B also shares sentences with these, for which no sentence is quoted: lymphoid tumor (1 paper).